INS (insulin)
Diseases named in the same sentence as INS in open-access papers (continued):
Sharing a sentence is not in itself a finding about the gene and the disease.
Insulin resistance (continued). "GDM patients are a heterogeneous cohort of women; some have insulin resistance in skeletal muscle or fat, some hepatic insulin resistance, and others have relatively normal insulin resistance but present with an insulin secretion defect." (PMID 39065137, 2024). "Insulin resistance is the inability of the body’s cells and tissues to respond appropriately to normal levels of insulin." (PMID 38610162, 2024). "The adverse effects of olanzapine, blamed for decreased insulin secretion and insulin resistance, were neutralised by diet-induced ketosis." (PMID 38674903, 2024). "In clinical terms, the term “insulin resistance” refers to the need for high levels of insulin to maintain normal glucose concentrations." (PMID 39770980, 2024). "Building up glucose and glucose-6-phosphate decreases the insulin-mediated glucose uptake contributing to insulin resistance." (PMID 38707092, 2024). "Insulin resistance is characterized by compensatory insulin secretion and reduced insulin responsiveness in target organs." (PMID 39239539, 2024). "In 3T3-L1 adipocytes, insulin resistance induced by chronic inflammation (chronic Tumour Necrosis Factor-alpha incubation, TNF) or hyperinsulinemia (chronic insulin incubation, CI) was sufficient to cause a marked downregulation of mitochondrial proteins." (PMID 38960128, 2024). "In this study, IUGR-C pigs exhibited significantly increased plasma insulin levels and HOMA-IR compared to NBW-C pigs, indicating insulin resistance, possibly associated with elevated FFA levels in tissues." (PMID 39281051, 2024). "In order to compensate for the increased insulin resistance, β-cells initially increase insulin secretion." (PMID 38472622, 2024). "Fasting plasma glucose and insulin were measured, and the homeostatic model assessment for insulin resistance was calculated." (PMID 39544568, 2024). "Second, free fatty acids in the bloodstream impact cellular responses to insulin, inducing increased insulin resistance." (PMID 38257092, 2024). "Concentrations of various biomarkers related to insulin or to peripheral insulin resistance have also been assessed in CSF and blood of subjects from various cohorts, including those with AD." (PMID 37611907, 2024). "Insulin resistance is defined as the failure of a normal biological response to endogenous and exogenous insulin." (PMID 39768981, 2024). "A characteristic of T2D is insulin resistance, in which the body cells cannot functionally use insulin despite a normal or even higher than normal circulating concentration." (PMID 39950097, 2024). "HOMA-IR represents the fasting plasma insulin (mU/L) × fasting plasma glucose (mmoles/L)/22.5 and is a test for insulin resistance." (PMID 38339127, 2024). "Firstly, we confirmed the successful development of insulin resistance in mature adipocytes using palmitic acid (16:0), assessed by insulin-stimulated glucose uptake." (PMID 39339765, 2024). "In its turn, obesity-driven insulin resistance increases the requirement for exogenous insulin, forming a vicious circle." (PMID 39335526, 2024). "Chronic exposure to elevated cortisol levels can lead to insulin resistance, reducing the responsiveness of the body’s cells to insulin." (PMID 39765947, 2024). "Chronic consumption of an HFD is associated with insulin resistance and altered glucose metabolism, partly due to impaired PI3K/Akt signaling in insulin-sensitive tissues such as the liver, muscle, and adipose tissue." (PMID 39554996, 2024). "T2DM is characterized by the development of reduced insulin sensitivity and subsequent insulin resistance, ultimately leading to poor glycemic control and prolonged episodes of severe hyperglycemia." (PMID 39596529, 2024). "Primary outcomes include fasting blood sugar, postprandial glucose, HbA1c, insulin levels, Homeostatic Model Assessment for Insulin Resistance (HOMA-IR), and C-peptide." (PMID 39483608, 2024).
Insulin resistance (continued). "Prediabetes, a state observed in patients without NGT, is characterized by glucose intolerance resulting from systemic insulin resistance, which is substantially compensated for by the oversecretion of insulin through mechanisms that remain elusive." (PMID 38713514, 2024). "Together with diminished pulsatility of insulin and downregulated insulin receptor number, chronic hyperinsulinemia increases DNL and causes hepatic insulin resistance." (PMID 39640841, 2024). "Conversely, insulin resistance results in elevated insulin needs, which impede glycemic control and weight management." (PMID 39135667, 2024). "These inflammatory factors increase insulin resistance by interfering with the insulin signaling pathway, further increasing blood glucose." (PMID 38464971, 2024). "The development of insulin resistance is usually balanced by an increased rate of insulin secretion due to β-cell hyperplasia, which contributes to the maintenance of normal maternal glucose levels." (PMID 39331227, 2024). "T2DM is a chronic metabolic disease characterized by abnormally high blood glucose levels, which are primarily due to insufficient insulin production or a weakening of the body’s response to insulin, known as insulin resistance." (PMID 39596859, 2024). "T2DM, a leading cause of global mortality, is characterized by hyperglycemia, chronic insulin resistance, and β-cell dysfunction, constituting a chronic metabolic disorder with progressive deterioration in cellular function and insulin secretion." (PMID 38930536, 2024). "Therefore, GH deficiency may be associated with reduced insulin sensitivity and insulin resistance." (PMID 38611940, 2024). "Probiotic supplementation reduces fasting plasma glucose, insulin resistance, insulin, and serum high-sensitivity C-reactive protein and elevates glutathione and antioxidant capacity." (PMID 38398870, 2024). "Ghrelin has been shown to inhibit insulin secretion, which can lead to increased blood glucose levels and potentially contribute to insulin resistance over time." (PMID 39519478, 2024). "It is strongly related to insulin resistance through direct mechanisms on insulin sensitivity and the expression of GLUT4, as well as insulin clearance." (PMID 38399531, 2024). "Insulin resistance – the failure of insulin to promote glucose uptake in its target tissues – is triggered by genetic and environmental factors such as family history of metabolic disease and high-calorie diets." (PMID 38329473, 2024). "The CNI drugs, especially tacrolimus, play an essential role in the PTDM pathophysiology, increasing insulin resistance and decreasing insulin release." (PMID 38352660, 2024). "Metabolic score for insulin resistance (METS-IR) is an index to assess cardiometabolic risk in healthy and at-risk individuals and a promising tool for screening of insulin sensitivity." (PMID 39110699, 2024). "We calculated the pregestational BMI related to insulin treatment and the significant elevation in homeostasis model assessment of insulin resistance (HOMA-IR) by receiver operating characteristics curve (ROC) analysis." (PMID 39803116, 2024). "This glucose-lowering effect is thought to result from improvements in insulin signaling, reduced insulin resistance, decreased hepatic glucose production, and increased energy expenditure." (PMID 39273597, 2024). "Studies have demonstrated that FMT from lean donors to individuals with metabolic syndrome can improve insulin sensitivity, highlighting the potential of gut microbiota manipulation as a therapeutic strategy for insulin resistance." (PMID 39659426, 2024). "Impaired glucose metabolism resulting from insulin resistance leads to inadequate glucose levels in the brain, compromising intracellular insulin signaling." (PMID 39596023, 2024). "SIRT3 expression reduction contributes to insulin resistance, and its overexpression enhances glucose uptake and reduces ROS production in insulin-resistant muscle cells 29,141,142." (PMID 38904020, 2024).
Insulin resistance (continued). "This accumulation triggers insulin resistance and affects the secretion of adipokines, thereby further impacting insulin signaling and glucose uptake." (PMID 38390200, 2024). "Several previous studies indicated that LGG increased insulin sensitivity by increasing adiponectin levels in mice with type 2 diabetes or insulin resistance." (PMID 38951898, 2024). "Shrimp oil improved (p < 0.05) oral glucose tolerance, insulin response, and homeostatic model assessment-estimated insulin resistance index, decreased serum insulin, leptin, HbA1c, and free FAs, while it also increased adiponectin." (PMID 39728129, 2024). "It has been demonstrated that the secretion of insulin after eating causes PI3K/AKT signaling pathway activation, which can serve to decrease obesity and insulin resistance." (PMID 39598345, 2024). "Adiponectin enhances insulin sensitivity, whereas resistin and pro-inflammatory cytokines (e.g., TNF-α) are associated with insulin resistance." (PMID 39683486, 2024). "Insulin resistance is often the core mechanism of dysregulated sugar and fat metabolism, and adipocyte metabolism is an important determinant of systemic insulin sensitivity." (PMID 38957396, 2024). "The insulin increase combined with euglycemia led to an increased calculated HOMA-IR in HE-BHB mice indicating insulin resistance compared to HE-CSF mice." (PMID 38553002, 2024). "The inhibition of lipolysis by insulin in adipose tissue is one of the other mechanisms that is impaired due to insulin resistance; it also leads to an increase in circulating FFA and worsened insulin resistance." (PMID 38892574, 2024). "This reversed hepatic insulin resistance, increased pancreatic insulin secretion, and lowered fasting and postprandial hyperglycemia." (PMID 39769002, 2024). "The homeostasis model shows that vitamin D and probiotics reduce serum insulin levels and insulin resistance." (PMID 38398870, 2024). "Further, understanding insulin resistance and the mechanisms of insulin action is critical for the continued development of effective therapeutic strategies to combat T2DM, which is a major challenge for the medical community." (PMID 38799166, 2024). "Given the heterogeneity of glucose and lipid metabolism in both GDM and prediabetes, accurately characterizing the degree of insulin secretion and insulin resistance defects in patients would allow for better treatment of GDM-related outcomes." (PMID 39065137, 2024). "It is well known that obesity is always accompanied by destructive glucose homeostasis and insulin sensitivity, and insulin resistance is intimately related to altered lipid profiles." (PMID 39063332, 2024). "In GD, the insulin signaling pathway undergoes a series of disruptions, each contributing to the impairment of glucose uptake and the development of insulin resistance." (PMID 39519193, 2024). "Glucose, insulin, triglyceride, and insulin resistance indices (HOMA-IR and TyG), as well as the activity of the antioxidant enzymes, increased in rats in the obese group." (PMID 39123622, 2024). "Insulin resistance is characterized by a reduced biological response of insulin-sensitive tissues to normal physiological concentrations of insulin." (PMID 38539930, 2024). "employed a concentration of 100 nM insulin for 36h to induce insulin resistance and studied the beneficial effect of ginsenoside-Rg1 on glucose metabolism in HepG2 cells." (PMID 39749015, 2024). "Insulin resistance, a hallmark feature of T2DM, arises from impaired insulin signaling in peripheral tissues such as skeletal muscle, liver, and adipose tissue." (PMID 39050565, 2024). "Brain insulin resistance (IR), characterized by reduced responsiveness to insulin effects, results in a relative insufficiency of brain insulin levels." (PMID 39073013, 2024). "Previous studies have indicated that lauric acid can exert antidiabetic effects, alleviate insulin resistance, and reduce hyperglycemia by restoring insulin and glucose homeostasis." (PMID 39463013, 2024).
Insulin resistance (continued). "This is explainable as insulin resistance (IR) stimulates insulin secretion, leading to an increased bone mineral density (BMD) by promoting osteoblast proliferation and inhibiting osteoclast activity." (PMID 39765929, 2024). "Insufficient insulin secretion and insulin resistance are two crucial factors in the pathogenesis of Type 2 diabetes." (PMID 38957446, 2024). "Insulin resistance is a condition in which cells become less responsive to insulin, impairing blood glucose control." (PMID 39458017, 2024). "The mechanism by which GlcN induces insulin resistance involves depletion of intracellular ATP, impairment of insulin signaling, and inhibition of GLUT4 translocation." (PMID 39749015, 2024). "In this regard, peripheral insulin resistance has been reported subsequent to central insulin dysregulation in a mouse model of AD." (PMID 39656485, 2024). "This study demonstrated that treatment with BPE, along with polyphenol compounds, led to a notable reduction in FBG and fasting insulin levels in mice, resulting in marked improvements in insulin resistance." (PMID 39765819, 2024). "At the same time, allicin can reduce serum glucose and insulin levels and reduce triglyceride and digestive tract fatty acid absorption, thereby improving insulin resistance and impaired glucose tolerance." (PMID 38612538, 2024). "Cortisol as a potent insulin-antagonistic hormone inhibits insulin secretion, promotes insulin resistance and hyperglycemia." (PMID 39744637, 2024). "A likely explanation is that prolonged high levels of insulin induce down-regulation and desensitization of insulin receptors, leading to insulin resistance." (PMID 38846018, 2024). "In this adaptation phase, β cells undergo functional changes that augment the sensitivity and capacity for stimulus-coupled insulin secretion in response to excess nutrient availability and/or insulin resistance." (PMID 38950317, 2024). "T2DM is more common than T1DM in clinical practices; it is characterized by a decrease in insulin sensitivity in tissues and is related to insulin resistance." (PMID 38683825, 2024). "It has various pharmacological effects, including antibacterial, anti-inflammatory, increasing insulin sensitivity, and reducing insulin resistance." (PMID 39456928, 2024). "Dysregulation of PTP1B activity has been implicated in insulin resistance and T2D and inhibition of PTP1B improves insulin sensitivity, glucose uptake, and glucose homeostasis in preclinical models." (PMID 38199575, 2024). "Previously characterised conditionally immortalised human kidney Pods20, GECs21, and MCs22, together with PTCs23, were used to model insulin sensitivity and insulin resistance." (PMID 39562547, 2024). "Primary HSC cultures from wild-type mice and from L-SACC1 transgenic mice that exhibit hyperinsulinemia and resultant insulin resistance due to a defect in hepatic insulin clearance were used." (PMID 40808720, 2024). "Elevated levels of LEAP-2 were found in mice and humans with liver steatosis and showed a positive correlation with fasting insulin, Homeostatic Model Assessment of Insulin Resistance, and liver fat content related to glucolipid metabolism." (PMID 38778244, 2024). "The exploratory results included changes in body weight, body composition, ketonemia, glycemia, insulin and insulin resistance (HOMA-IR), blood lipids, inflammatory markers, and self-reported changes in menses." (PMID 39150916, 2024). "Incubation in high glucose medium for 24 h produced insulin resistance, as measured by decreased insulin-induced tyrosine phosphorylation (activation) of IRS1." (PMID 39119463, 2024). "It is characterized by increased basal plasma glucose levels and insulin levels, which we consider physiological insulin resistance." (PMID 38875221, 2024). "Glucose tolerance disorders are a common complication in the post-renal transplantation period, and they are characterised by a combination of insulin resistance and insulin hyposecretion." (PMID 38474169, 2024).
Insulin resistance (continued). "For both analyzed compounds, CA and 1,2-diCA-PC, we confirmed previous observations that CA and 1,2-diCA-PC increase insulin-stimulated glucose uptake in adipocytes with previously developed insulin resistance." (PMID 39339765, 2024). "This low-grade inflammation, termed metabolic endotoxemia, disrupts insulin signaling pathways, exacerbates insulin resistance, and accelerates the progression of T2D." (PMID 39770729, 2024). "Insulin resistance impairs the ability of insulin to suppress hepatic production of very low-density lipoprotein (VLDL), leading to increased triglyceride levels." (PMID 39310549, 2024). "HFD-fed animals displayed significant increase in body weight and systemic insulin resistance as evidenced by impaired glucose tolerance, reduced insulin responsiveness and an increase in the HOMA-IR index value, as compared to the LFD group." (PMID 39178212, 2024). "These associations suggest that multiple metabolic factors contribute to insulin sensitivity, particularly in patients with higher baseline insulin resistance." (PMID 39218890, 2024). "Probiotics and selenium reduce fasting plasma insulin resistance, serum insulin levels, glucose levels, and insulin sensitivity." (PMID 38398870, 2024). "Insulin resistance impedes the binding between insulin and its receptors, consequently diminishing the protective effect of insulin on joints and further facilitating the advancement of OA." (PMID 38332532, 2024). "Insulin resistance promotes hypertriglyceridemia and vice versa, mainly as visceral adipocytes exhibit heightened resistance to insulin." (PMID 39440341, 2024). "Mechanistically, IPH was reported primarily due to deterioration of insulin secretion and, to a lesser extent, to insulin resistance." (PMID 39119006, 2024). "Compared to other women with PCOS, women with PCOS who have a body mass index (BMI) in the obesity range have poorer reproductive and metabolic outcomes, including higher androgens, fasting glucose, fasting insulin, insulin resistance, and lipids." (PMID 39516828, 2024). "First, the emerging insulin resistance of peripheral tissues leads to excessive insulin synthesis, and both factors lead to prediabetes and then to T2D." (PMID 39210428, 2024). "Decreased transport of insulin from peripheral circulation to the brain, and insulin resistance are the result of hypothalamic inflammation due to inflammaging." (PMID 39518747, 2024). "As expected, the HFD group had higher insulin secretion and presented insulin resistance compared to the SD." (PMID 38399437, 2024). "Evaluation of insulin sensitivity in hepatocytes has shown a significant retrieval from insulin resistance." (PMID 39759127, 2024). "The role of fetuin-A in impairing insulin sensitivity is further supported by the fact that fetuin-A knockout (KO) mice are protected from weight gain and insulin resistance." (PMID 39409124, 2024). "The ultimate reason behind these derangements is insulin resistance (IR), a physiological condition in which cells are unable to react to the hormone insulin as they normally should." (PMID 38770513, 2024). "And cirrhosis leads to impaired insulin clearance from the liver, resulting in pancreatic β-cell dysfunction and peripheral insulin resistance, consequently increasing the risk of T2D." (PMID 38646627, 2024). "Participants with brain insulin resistance struggled to lose weight or reduce their visceral fat, whereas those with good brain insulin responsiveness achieved substantial benefits." (PMID 38363340, 2024). "With insulin resistance, insulin production first increases, which overburdens the ER where proinsulin synthesis and folding occur." (PMID 38744890, 2024). "The common direct implications of both obesity and insulin resistance (up to type 2 diabetes) in MS have suggested their combination, i.e., an insulin-centered “diabesity” as a nuclear or main defining pathology of the syndrome." (PMID 38396928, 2024).